CDC25C (cell division cycle 25C)
Diseases named in the same sentence as CDC25C in open-access papers (continued):
Sharing a sentence is not in itself a finding about the gene and the disease.
cancer (continued). "Gene expression analysis showed that clonogenic side population cells in cancers express genes involved in the cell cycle and mitosis (e.g., SKA1, CCNB1, CDC25C, CDC2, BIRC5, CENPE, AURKB, KIFs, TOP2A, ASPM) more strongly than non-side population cells." (PMID 23962337, 2013). "By phosphorylating CDC25C irrespective of DNA damage, Pim kinases induce uncontrolled proliferation of cancer cells." (PMID 40165380, 2025). "CDC25C was a key target through which APs impact HCC and multiple other cancers." (PMID 41019083, 2025). "This methodology has the potential for identifying the critical regulatory genes involved in maintaining cell cycle coherent oscillation, such as CDC25C, CCNE2, KPNA2, etc., which may be the new targets in cancer." (PMID 38353329, 2024). "Firstly, we evaluated the mRNA expression of six DDR-related genes in NSCLC tissues in GEPIA, which demonstrated that CDC25C, NEIL3, H2AFX, NBN, XRCC5 and RAD1 were all significantly higher expressed in NSCLC cancer tissues compared to with normal lung tissues." (PMID 36408135, 2022). "Suppression of TOPK weakened phosphorylation of both CHK1 and Cdc25C after exposure to HU alone and when combined IR, indicating that S-phase and G2M checkpoints are impaired for proliferating cancer cells in the absence of TOPK." (PMID 33168956, 2021). "However, CDC25C was only upregulated in T2-KD OVCAR4 and JOSH2 cancer cells compared to their corresponding control cells and there was no change in the expression of CDC25A in any of the T2-KD cells compared to its respective controls." (PMID 33023532, 2020). "This study further identified an 11 amino acid motif within the LIM domain (eLIM) that interacts with CHK2/CDC25C, blocks CHK2-CDC25 and CDC25/14-3-3 interactions, enhances CDC25 activity and consequently, promotes cancer radiosensitivity via mitotic catastrophe and apoptosis." (PMID 32587768, 2020). "α-Pinene, at 1000 μg/mL, inhibited the human carcinoma hepatocellular BEL-7402 cells proliferation, arresting cell growth in the G2/M phase of the cell cycle, decreasing gene and protein expressions of Cdc25C, and reducing the cycle dependence on kinase 1 (CDK1) activity." (PMID 32527068, 2020). "Many cancers have been reported to overexpress CDC25A and CDC25B, but CDC25C has not previously been associated with cancer outcome." (PMID 27775025, 2016). "Because BA-j can capture ·O2− and selectively increase the level of H2O2 in cancer cells rather than normal cells, which can oxidize CDC25C, and the dephosphorylation of CDK1is inhibited, but not other CDKs, thus inhibiting cell proliferation." (PMID 26330167, 2015). "Several anticancer agents have been noted to mediate such G2/M phase arrest in cancer cells through multiple mechanisms: downregulation of CDK1-cyclin A/B complexes, inactivation of Cdc25C activity, and disruption of tubulin polymerization and spindle assembly." (PMID 25342427, 2014). "The phospho-CDC25C (Ser 216) has to our knowledge not been previously investigated in any human cancer." (PMID 20500813, 2010). "It is known that Pim kinases act on the proliferation of cancer cells by interfering with the cell cycle checkpoints, by phosphorylating cell division cycle 25 (CDC25) family members that are important regulators of the G1/S (CDC25A,) and G2/M (CDC25C,) checkpoints." (PMID 40165380, 2025). "Besides the ability to inhibit NF-κB/STAT3, we show that GL may target cancer cell progression by the activation of ATM/ATR pathway, inducing a rapid CDC25C degradation in DU145 cells." (PMID 26683224, 2016). "The significant downregulation of CDC25C post-C/T in Late Recurrence patients but not in Early Recurrence patients suggests that HGSOC patients in whom C/T induces cell cycle arrest are more likely to experience delayed recurrence of cancer, as one would expect." (PMID 37435088, 2023).
cancer (continued). "Mechanistically, it was observed that in cancer cells independent of KIF22’s microtube-dependent function, KIF22 binds to and transcriptionally represses the promoter region of Cdc25C, an inhibitor of mitosis termination." (PMID 38989461, 2024). "In addition, the expression of CDC25C (P = 0.000), pCDC25CSer216 (P = 0.000), CDK1 (P = 0.000), CHK1 (P = 0.000), CHK2 (P = 0.000), PLK1 (P = 0.000) and Aurora A (P = 0.008) between the primary carcinoma without metastasis and serious borderline cystadenoma were also statistically different." (PMID 32393310, 2020). "The hitherto unknown ability of HMGA2 to regulate nuclear CDC25C content independent of pCDC25CS216 status requires further investigations and may be clinically relevant as low cellular HMGA2 levels promote the emergence of cancer cell populations with heterogeneous telomere phenotypes." (PMID 26799419, 2016).
tumor (80 papers, 2004 to 2026). "CDC25C, a cell cycle regulatory protein, has been confirmed to be associated with tumorigenesis and tumor progression." (PMID 35574406, 2022). "Here we demonstrated that a higher CDC25C expression was associated with shorter survival and lower response to ICIs, as well as an immunosuppressive tumor microenvironment, in patients with LUAD." (PMID 35574406, 2022). "CDC25C is differentially overexpressed in basal tumor cells and is associated with dedifferentiation of tumor cells." (PMID 32518522, 2020). "We propose CDC25C is differentially overexpressed in basal tumor cells and associates with tumor cell dedifferentiation." (PMID 27775025, 2016). "As a Ca2+-permeable cation channel, TRPM8 mediates intracellular Ca2+ signaling transduction and interferes with the cell cycle via CamKII, cdc25C, and cdc2, thereby promoting tumor cell proliferation and the development of radioresistance." (PMID 40535121, 2025). "CDC25C is involved in regulating the G2/M phase and mediating DNA damage and repair, as well as a key part of tumorigenesis and tumor development 47-49." (PMID 39247594, 2024). "Our findings here demonstrated that LAS exerts anti-tumor effects by inhibiting PLK1/CDC25C and PLK1/AKT pathways." (PMID 38495493, 2024). "Recently, the expression of CDC25C has been closely related to tumorigenesis and tumor development and can be used as a potential target for radiation therapy." (PMID 38673980, 2024). "For decades there has been a strong movement toward understanding the roles of CDC25C in tumor progression." (PMID 36675024, 2023). "We demonstrate that well-differentiated LUAD tumors express low levels of CDC25C, whereas poorly differentiated LUAD tumors express high levels of CDC25C, thereby linking the expression of CDC25C with aggressive histological features of the tumor." (PMID 36830899, 2023). "In particular, because the mRNA levels of all three isoforms of CDC25—namely CDC25A, CDC25B and CDC25C—are elevated in this type of tumor." (PMID 36830899, 2023). "In our previous study, miR-142-3p was identified as a tumor suppressor and led to G2/M arrest through targeting CDC25C." (PMID 37403081, 2023). "First, our study is the first to test the link between LUAD tumor differentiation grade and the expression of CDC25C in the tumor." (PMID 36830899, 2023). "In our previous study, miR-142-5p was identified as a tumor suppressor functioned by regulation of CDC25C." (PMID 37403081, 2023). "As such, our study comprehensively documents CDC25C protein expression in distinct areas of the tumor." (PMID 36830899, 2023). "More recently, two studies reported that CDC25C mRNA levels in LUAD influence the tumor immune cell infiltration, as well as its response to immunotherapy." (PMID 36830899, 2023). "It has been reported that increased expression of ILP-2 prevents the inhibitory activity of CHK2 on CDC25C, thereby promoting the transition of the tumor cell cycle from G2 to M phase and supporting tumor cell proliferation." (PMID 35814477, 2022). "High RAB20 expression promotes tumor progression and cell proliferation, inducing G2/M cell cycle arrest via the Chk1/cdc25c/cdc2-cyclinB1 pathway." (PMID 35267417, 2022). "Western blot analyses from infigratinib‐resistant tumour collected at different passages indicated an elevation in cell cycle proteins such as cyclin E2, cyclin B1, Cdc25C, p‐Cdc2, cyclin D1, Rb and p‐Rb." (PMID 33179425, 2021). "Cell division cycle 25C (CDC25C) can inhibit apoptosis in various tumor types, including NSCLC, through regulation of the G2/M-phase transition and FAS pathway." (PMID 33988228, 2021). "Compared to the vehicle group, the expressions of Cdc25C and CyclinB1 in the tumor tissues were significantly decreased in TAIII-treated groups." (PMID 33628174, 2020).
tumor (continued). "The regulation of CDC25C in the cell cycle is affected by multiple signaling pathways and closely related to tumorigenesis and tumor development." (PMID 32518522, 2020). "By testing the expression of CDC25C antibody in the serum of patients with tumor, it can help to their diagnosis and treatment." (PMID 32518522, 2020). "The available results indicate that some patients with tumors already have the immunogenicity of CDC25C, and thus CDC25C has become a new tumor marker." (PMID 32518522, 2020). "Clinical tumor biopsy specimens were analyzed by immunohistochemistry and high expression of CDC25C was detected in 27/56 (48.2%) patients." (PMID 32518522, 2020). "In nude mouse models with prostate cancer xenografts, physapubescin B (50 mg/kg) decreased PC3 tumor growth by reducing the expression levels of Ki-67, Cdc25C, and full length PARP and increasing the apoptotic cell population within the tumor tissue." (PMID 32116665, 2019). "Based on these findings, we selected CDC25C, a top-ranked gene correlated with tumor cell dedifferentiation, for further validation." (PMID 27775025, 2016). "To confirm the mechanism by which SL4 retards tumor growth, we also examined the expression levels of proteins in the xenograft tumors, including the cell cycle proteins p21 and cdc25C, and the cell proliferation marker PCNA." (PMID 27819344, 2016). "Taken together, these findings demonstrated that CDC25C overexpression is characteristic of un-differentiated basal tumor cells, as well as basal tumor subtypes." (PMID 27775025, 2016). "Inhibiting CDC20 stabilized p21CIP1/WAF1, resulting in repression of several genes critical to tumor growth and survival, including CDC25C, c-Myc and Survivin." (PMID 25938542, 2015). "Based on the therapeutic efficacy of HAR in vivo model, the expressions of p21, p-Cdc2 and p-Cdc25C were examined in the tumor samples." (PMID 26678950, 2015). "Aberrant expression of Cdc25C can lead to abnormal cell cycle progression, tumor initiation and progression." (PMID 23637932, 2013). "The upregulation of CHK1 and CDC25C genes was independently verified by quantitative real-time PCR on cDNA synthesized from two normal retina and eight tumor samples." (PMID 20664703, 2010). "Activated Chk1 and Chk2 increase the expression of cell cycle checkpoint proteins, including Cdc25A and Cdc25C, leading to higher levels of G2/M arrest in tumor cells treated with NPRL2 and cisplatin than in tumor cells treated with cisplatin only." (PMID 20700484, 2010). "The fact that overexpression of CDC25C was associated with advanced FIGO stage, presence of lymph node metastases, large tumor diameter and poor differentiation indicate that high level of CDC25C is an event occuring late in the tumor development." (PMID 20500813, 2010). "Cdc25C, a phosphatase that mediates the conversion of Cdc2 from an inactive to an active form was found to have unchanged levels in the tumours." (PMID 18349838, 2008). "However, chronic overexpression of CDC25C upregulates PD-L1 in tumor cells through the STAT3/IRF1 pathway, and promotes the recruitment of Tregs, MDSCs and M2-like macrophages (M2) via chemokines such as CXCL10." (PMID 41019083, 2025). "Dovetailing with past work at the mRNA level, our findings demonstrate that CDC25C can indeed be detected in LUAD tumor sections by immunohistochemistry and that high CDC25C expression levels in the tumors are associated with aggressive histological features and with poor clinical outcomes." (PMID 36830899, 2023). "Furthermore, the tumor recurrence rate among patients with pathological stage I disease (n = 30) was significantly lower in patients whose tumors expressed low levels of CDC25C (p < 0.05)." (PMID 36830899, 2023).
tumor (continued). "In addition, high CDC25C mRNA levels in the tumor were shown to correlate with expression of genes that drive immune suppression." (PMID 36830899, 2023). "Furthermore, by using newly established PSCC cell lines and animal models, we demonstrated that RAB20 promotes cell proliferation and tumor progression, inducing the G2/M phase cell cycle via the Chk1/cdc25c/cdc2-cyclinB1 pathway." (PMID 35267417, 2022). "Currently, CDC25C has been found to play a pro-tumor role in various tumors." (PMID 35574406, 2022). "SLAMF1 and CDC25C were also identified as anti-tumor biomarkers in CRC." (PMID 36506313, 2022). "In addition, CDC25C expression was significantly associated with immune cell infiltration and immune-related signatures in the LUAD tumor microenvironment." (PMID 35574406, 2022). "A significant decrease in tumor weights was observed in the experimental group compared to the control, and an increase in Egr1 expression was noticed along with a decrease in cyclinB1 and CDC25c expression." (PMID 34638282, 2021). "It is reported that miR-142-3p could directly regulate the expression of CDC25C, induce G2/M phase arrest and inhibit the proliferation of tumor cells." (PMID 32518522, 2020). "As over-expression of cdc25C in the 14-3-3γ-knockdown cells led to an increase in centrosome number, we wished to determine if the increase in centrosome number affected cell survival and tumor formation." (PMID 27253419, 2016). "This also suggests that complete disruption of the cdc25C-14-3-3 complex during interphase might be a way to inhibit tumor growth and selective tumor cell killing." (PMID 27253419, 2016). "Furthermore, CDC25C overexpression in tumor tissues has been observed which underscores an oncogenic function of CDC25C." (PMID 26595675, 2015). "All tumor samples showed elevated gene expression of CHK1 as well CDC25C at the level of mRNA." (PMID 20664703, 2010). "We also noted that CDDP-treatment of pxn100 tumours induced the expression by >2.5-fold of genes encoding proteins that regulate the G2M cell cycle checkpoint (WEE1, CCNB1, CDC25C) and a gene encoding a protein involved in the anaphase promoting complex in mitosis (CDC6)." (PMID 15452549, 2004). "In addition, higher CDC25C expression correlated with a later T-stage, N-stage, M-stage, and pathological stage, suggesting that CDC25C could be a potential biomarker for tumor staging." (PMID 35574406, 2022). "In our study, CDC25C was significantly associated with the infiltration levels of multiple immune cells, with negative correlations with anti-tumor immune cells (CD8+ T cells, B cells, NK cells, and DC), but positive correlations with immunosuppressive immune cells (Th2 and Treg cells)." (PMID 35574406, 2022). "In addition, CDC25C gene suppression in 5926 cells using siRNA significantly decreased the percentage of triple positive cells from 66% to 38% (P = 0.0043) and arrested tumor cell growth." (PMID 27775025, 2016). "CDC25C, HMMR, and PRR11 exhibited focal areas of increased expression, indicating spatial variation in functional states within the tumor." (PMID 41602397, 2026). "During the G2/M phase, the diphosphatase CDC25C removes the inhibitory phosphorylation sites Thr14 and Thr15 from CDK1, activating it and directing tumor cells into mitosis." (PMID 39949984, 2025).